IL1B (interleukin 1 beta)
Diseases named in the same sentence as IL1B in open-access papers (continued):
Sharing a sentence is not in itself a finding about the gene and the disease.
lung disease (continued). "We acknowledge that focusing on NETs and IL-1β in this manuscript is somewhat subjective and several other mechanisms of the innate immune system take place in the lungs of PwCF that could drive lung disease." (PMID 40791588, 2025). "A characteristic of CF lung disease is the infiltration of neutrophils releasing NETs that could be potentially enhanced by IL-1β." (PMID 40791588, 2025). "Therefore, understanding the interplay between IL-1β and NETs is crucial for addressing CF lung disease progression." (PMID 40791588, 2025). "Additionally, our results implicating a major role for NLRP3 in driving neutrophil responses are also consistent with studies involving inhibition of the NLRP3 inflammasome or IL-1β itself in other lung disease models." (PMID 40119408, 2025). "Our results strongly suggest that fine modulation of DATPs by the IL-1β-mediated transient inflammatory niche during injury repair is critical for effective lung restoration and is a potential therapeutic adjunct for treating lung diseases." (PMID 32750316, 2020). "We demonstrate here in vitro in epithelial cells and in vivo in three independent models (two involving mice given IAV +/– P.a, and one involving mice given IAV +/– IL-1β) that IAV promotes secondary P.a-mediated lung disease or augmented IL-1β-mediated inflammation." (PMID 32117268, 2020). "may play a critical role in lung diseases by modulating the expression of IL-17 through the modulation of IL-1β." (PMID 25853810, 2015). "In addition, T-helper (Th)-17 cells induced the production of pro-inflammatory IL-17, and are implicated in the pathogenesis of lung disease, and their activation in the presence of a combination of TGF-β, IL-6, and IL-1β mediated these pro-inflammatory differentiation." (PMID 36877411, 2023). "Moreover, NLRP3-derived cytokines (e.g., IL-1β, IL-18) appear to be the main inducers of a cytokine cascade (involving IL-23, IL-17, IL-26, IL-6, IL-13, and IL-5) that is responsible for the development of pulmonary diseases in morbidly obese subjects." (PMID 35806353, 2022). "Hence, blocking IL-1β levels could ameliorate the lung inflammatory response in pulmonary disease patients." (PMID 29254155, 2017). "IL-6, IL-1β, MIP-2, and iNOS are well known to be important for the development and worsening of lung disease." (PMID 39052574, 2024). "IL-6, TNF-α, IL-1β, and MIP-2 are representative pro-inflammatory cytokines and chemokines that are related to the pathogenesis of various lung diseases." (PMID 35326218, 2022). "Besides the involvement in the antimycobacterial response, these compounds are also related to the extent of pulmonary disease, for which their increased presence during advanced disease may be more compatible with an inflammatory role, as is the case of increased IL-1β transcripts." (PMID 34506568, 2021). "MIF controlled the production of other cytokines such as IL-1β, IL-6, IL-8 and TNF-α in neonatal lung diseases." (PMID 33356032, 2021). "Genes showing altered expression include a number of genes known to play important roles in lung disease such as α1-antitrypsin (SERPINA1), transforming growth factor β 1 (TGFβI), interleukin 1 receptor 1 (IL1R1) and IL6, IL8, IL1B, IL1A." (PMID 28335732, 2017). "Our results, showing the role of IL-1β in modifying TNF-α-induced pulmonary inflammation, are in support of a consideration for IL-1β neutralization in treatment of acute, and potentially chronic, TNF-α mediated lung diseases." (PMID 19901996, 2009). "SiO2 and other particle exposure are known to be correlated with an increased risk of systemic autoinflammatory diseases, cardiovascular events, and lung disease, such as COPD, which are also strongly related to IL-1β, and that can benefit from IL-1β blocking treatment." (PMID 33144845, 2020). "Our studies establish a novel crosstalk between IL-21 and IL-1β, and this crosstalk may contribute to the uncontrolled inflammatory responses during PVM-induced lung disease." (PMID 26269257, 2015).
lung disease (continued). "IL-1β may enhance TNF-α-induced neutrophil recruitment to the lung by altering TNF receptors as well as MIP-2 and KC production in pulmonary diseases." (PMID 24696530, 2014). "In order to demonstrate the validity of the in vitro THP-1 model as a valuable tool in revealing possible bioactive nanomaterials, a regression analysis of IL-1β release at 25 mg/ml in the THP-1 cells to pathology scores was done, using the THP-1 results as the predictor variable for lung disease." (PMID 24225053, 2013). "Therefore, it appears that lung diseases are promoted by the secretome from dysfunctional adipose tissue, the altered adipokine profile of which drives NLRP3 inflammasome activation and subsequent production of IL-1β and IL-18." (PMID 35806353, 2022). "We speculate that similar mechanisms could be involved in TS during lung diseases as lung diseases of both noninfectious and infectious origin exhibit increased IL-1β levels and LOX-1-dependent acute inflammation." (PMID 35008850, 2021).
experimental autoimmune encephalomyelitis (54 papers, 2011 to 2025). An autoimmune demyelinating disease of the central nervous system that is produced experimentally in animals by the injection of homogenized brain or spinal cord in Freund's adjuvant. "It has recently been demonstrated in experimental autoimmune encephalomyelitis (EAE) that IL-17A recruits IL-1β-secreting myeloid cells that prime pathogenic γδT17 and Th17 cells, whereas mice with HIF-1α-deficient T cells are resistant to induction of Th17-dependent EAE." (PMID 36961533, 2023). "Specifically, Tlr4-mediated NF-κB activation drives the upregulation of proinflammatory cytokines (IL6, IL1β, and TNFα), which is consistent with its role in amplifying microglial reactivity in experimental autoimmune encephalomyelitis." (PMID 40563324, 2025). "We identified that Bhlhe40 in CCR6high MP CD4+ T cells as a key regulator of GM-CSF expression through IL-23 and IL-1β signaling, contributing to central nervous system (CNS) pathology in experimental autoimmune encephalomyelitis." (PMID 37121980, 2023). "Overload of IL-1β secretion have been shown to promote demyelination and deteriorate the severity of inflammatory neurodegenerative experimental autoimmune encephalomyelitis." (PMID 36589291, 2022). "In vivo studies have shown that MCC950 reduced IL-1β production and attenuated the severity of experimental autoimmune encephalomyelitis (EAE)." (PMID 35874775, 2022). "IL-1β is a potent pro-inflammatory cytokine that plays a significant role in the pathogenesis of experimental autoimmune encephalomyelitis (EAE)." (PMID 33143271, 2020). "IL-1β production by CNS-infiltrating neutrophils and monocytes is required for the development of experimental autoimmune encephalomyelitis, which can be partially replicated by injection of IL-1β." (PMID 33391257, 2020). "IL-1β is involved in hypersensitivity of many pain models, such as pain in experimental autoimmune encephalomyelitis, sciatic pain, and CFA-induced inflammatory pain." (PMID 30755236, 2019). "The involvement of IL-1β and the inflammasome in experimental autoimmune encephalomyelitis (EAE), a commonly used animal model for MS, has been confirmed in different studies." (PMID 27266875, 2016). "Additionally, we examined IL-10 impact on synaptic transmission in striatal medium spiny neurons and its role in counteracting inflammatory synaptopathy induced by IL-1β in female C57BL/6 mice with experimental autoimmune encephalomyelitis (EAE)." (PMID 39169949, 2024). "Classical inflammatory CD14++CD16− monocytes, with high CD192 (also known as CCR2, a chemokine receptor that binds monocyte chemoattractant proteins, MCP-1) expression, due to interleukin-1β (IL-1β) secretion cross the blood–CNS barrier before experimental autoimmune encephalomyelitis onset." (PMID 37893243, 2023). "Addition of exogenous IL-1β to Th cell cultures enhanced in vitro Th17 cell differentiation and IL-1R1-deficient T cells failed to induce Th17-driven disease in murine experimental autoimmune encephalomyelitis (EAE)." (PMID 36389679, 2022). "Moreover, Nrf2 suppresses lipopolysaccharide-mediated macrophage inflammatory response by blocking IL-6 and IL-1β transcription, in Experimental autoimmune encephalomyelitis (EAE) mouse models." (PMID 32380663, 2020). "In a model of multiple sclerosis—experimental autoimmune encephalomyelitis (EAE)—mice deficient in cathepsin Z consistently developed lower levels of neuroinflammation and displayed disproportionally lower levels of circulating IL-1β." (PMID 28486971, 2017). "Pathological levels of IL1β impede synaptic long-term potentiation whereas elevated TNFα contributes to early synaptic abnormality in somatosensory cortex in mouse models of experimental autoimmune encephalomyelitis." (PMID 28769762, 2017). "Moreover, in the same study, exogenous ghrelin suppressed spinal cord levels of TNF-α, IL-1β and IL-6 mRNA in a mouse model of experimental autoimmune encephalomyelitis (EAE)." (PMID 23509933, 2013).
experimental autoimmune encephalomyelitis (continued). "Additionally, IL-25 may suppress Th17 cell responses through downregulation of IL-23, IL-1β, and IL-6 expression in activated dendritic cells which may protect mice from severe experimental autoimmune encephalomyelitis." (PMID 34956328, 2021). "Furthermore, mice deficient in both IL-1α and IL-1β do not develop experimental autoimmune encephalomyelitis (EAE), which is caused by pathogenic TH17 cells." (PMID 31840109, 2019). "In experimental autoimmune encephalomyelitis, BBG-dependent P2 × 7R antagonism resulted in decreased BBB damage with normalized levels of PDGFβR and claudin-5 and pro-inflammatory cytokines, IL-1β, IL-6, and TNF-α." (PMID 39342243, 2024). "Microglia-specific TAK1 KO mice showed decreased expression and release of IL-1β and TNF-α in CNS in animal models of experimental autoimmune encephalomyelitis and experimental stroke." (PMID 36862288, 2023). "For example, IL-1β induces CXCL-10 in astrocytes in culture, but it is also expressed by macrophages and has been shown to exacerbate experimental autoimmune encephalomyelitis." (PMID 25323767, 2014). "This is similar to what was observed in rodent models of experimental autoimmune encephalomyelitis (EAE), where expression of IL-1β activated and translocated NF-ΚB to the nucleus and induced expression of inflammatory cytokines, IL-1β and TNF-α, as well as the IL-10." (PMID 38938553, 2024). "It is important to recall that the direct involvement of the NLRP3 inflammasome in the onset and development of MS has been demonstrated in the experimental autoimmune encephalomyelitis (EAE) animal model, which justifies the particular relevance of IL-1β in MS." (PMID 37693246, 2023). "Likewise, in the preventative and therapeutic experimental autoimmune encephalomyelitis model (EAE), high doses of VPA (500 mg/kg) reduced transcript levels of TNFα, IL-1β and iNOS in the EAE spinal cord." (PMID 36412793, 2022). "Several studies have shown increased levels of the cytokines TNF-α, IL-1β, and IL-6 in the DRG of animals with chronic pain induced by chemotherapeutic paclitaxel, chronic constriction of the sciatic nerve, experimental autoimmune encephalomyelitis, operation, or inflammation." (PMID 33355900, 2021). "IL-23 combined with IL-1β promotes the expression of IL-17 by γδT cells in the absence of additional signals in experimental autoimmune encephalomyelitis." (PMID 28912779, 2017).
neuroblastoma (54 papers, 2007 to 2026). Neuroblastoma (NB) is the most common solid, extracranial childhood tumor. "We also observed that neuroblastoma cells exposed to EVs from QKI-depleted HeLa cells expressed significantly more IFNA1 and IL1B mRNA than did neuroblastoma cells exposed to EVs from control shRNA-treated cells." (PMID 39308343, 2024). "Sage even increased MCP-1, IL-6, IL-8 and ICAM-1 highly significantly in neuroblastoma (SK-N-SH) cells in a non-IL-1β treated group in 4 h and MCP-1 and ICAM-1 in 24 h." (PMID 39408750, 2024). "To address this issue, we treated SH-SY5Y human neuroblastoma cells with IL-1β, a proinflammatory cytokine released by activated microglia and other cells, and monitored the protein expression of tau." (PMID 37552543, 2023). "IL-1β and TNFα from these macrophages stimulated arginine metabolism in neuroblastoma cells, promoting tumor cell proliferation." (PMID 38087370, 2023). "The K vitamins, indeed, were able to reduce the inflammatory response via NF-kB signaling pathway inactivation, which, in turn, resulted in significantly suppressing the expression of IL-1β and IL-6 in neuroblastoma cells." (PMID 38201262, 2023). "Previous investigations have reported that rutin inhibits the production of proinflammatory cytokines in microglia by lowering TNF-α and IL-1β levels in human neuroblastoma ( SH-SY5Y ) cells." (PMID 36139918, 2022). "Our previous studies showed that reactive oxygen species (ROS) and inflammatory cytokines, such as TNF-α, IL-1β, and IL-6, induced FtMt expression in the human neuroblastoma cell line IMR-32." (PMID 35008961, 2022). "We tested the effect of exposing human neuroblastoma SH-SY5Y cells to IL-1β, TNF-α, and IL-6 on thiamin uptake." (PMID 35750148, 2022). "Certain miRNAs presented in the mouse brain suppress IL-1β secretion as well as JEV replication in neuroblastoma cells." (PMID 36016430, 2022). "The current study focuses on the effects of AM404 and acetaminophen in human SK-N-SH neuroblastoma cells by evaluating IL-1β-induced neuroinflammatory and oxidative endpoints, such as PGE2-and 8-iso-PGF2α-concentrations, and the underlying mechanisms." (PMID 34867421, 2021). "A potential pro-inflammatory effect of PMU on the nervous system cells was assessed measuring the levels of the cytokines TNF-α and IL-1β in the supernatant of PMU-treated cultures of neuroblastoma or microglial cells." (PMID 34281258, 2021). "Acetaminophen exhibits antitumoral properties in neuroblastoma cells at least in part by reactive oxygen species and IL-1β, along with NF-κB and p65 upregulation." (PMID 33205044, 2020). "CCL2 was also found to promote apoptosis and secretion of TNF-α and IL-1β in neuroblastoma SH-SY5Y cells and inhibit cell viability, while the knockdown of CCL2 exerted the opposite effects." (PMID 30761072, 2019). "Transfection of miR-155 induced robust mRNA expression of IL-1β, IL-6, and IL-15 in neuroblastoma cells at 24 h after WNV NY99 infection." (PMID 31861621, 2019). "After treating with Aβ1–42 for 6 h, PGC-1α prevents neuroblastoma cells from death and largely reduces the level of IL-1β and TNF-α." (PMID 28946859, 2017). "In SK-N-SH neuroblastoma cells and human bronchial muscle cells, expression of inflammatory mediators induced by IL-1β alone or in combination with other cytokines was reduced through p38 MAPK inhibition." (PMID 28245546, 2017). "Similar observations were reported in endothelial and neuroblastoma cells where morphine and IL-1β co-treatment increased MOR expression, which further substantiated our data." (PMID 23164507, 2012). "Since we previously detected that AAP induced an increase in caspase 1 activity in neuroblastoma cells and that the IL-1β gene contains the NFkB response element in its promoter region, we decided to analyze IL-1β levels in AAP-treated SH-SY5Y cells." (PMID 23166834, 2012).
neuroblastoma (continued). "The results presented here suggest that AAP activates the intrinsic death pathway in neuroblastoma cells through a mechanism involving NFkB and IL-1β." (PMID 23166834, 2012). "In human neuroblastoma cells the toxic actions involve ROS production, NFkB p65 activation and IL-1β production." (PMID 23166834, 2012). "Our results show that AAP activates the intrinsic apoptotic pathway in neuroblastoma cells through a mechanism involving ROS production, NFkB translocation to the nucleus, IL-1β production, Bax translocation to mitochondria and cytochrome c release." (PMID 23166834, 2012). "The increase in PGE2 production was similar to that found when SH-SY5Y human neuroblastoma cells were incubated with IL-1β (10 ng/ml)." (PMID 17204142, 2007). "Basal COX-2 mRNA expression in SH-SY5Y human neuroblastoma cells was up-regulated by treatment with ATRA to a similar extent than that found in cells treated with IL-1β (10 ng/ml)." (PMID 17204142, 2007). "Additionally, incubating neuroblastoma cell lines with human monocytes increased IL-1β and TNFα-expressing macrophages, signifying an M1 phenotype via AKT phosphorylation." (PMID 38087370, 2023). "Similarly, our data demonstrated that transfection of miR-155 mimic induced robust mRNA expression of IL-1β, IL-6, and IL-15 in human neuroblastoma cells." (PMID 31861621, 2019). "Stimulation of neuroblastoma cells with serum, TNFα or IL-1β increased chemerin secretion." (PMID 29221117, 2017). "Furthermore, we demonstrated that the pro-inflammatory cytokines TNFα and IL-1β as well as serum components stimulate chemerin secretion by neuroblastoma cells." (PMID 29221117, 2017). "Prolonged bath application of TNFα or IL-1β (6–8 h) to dissociated SC neurons or SC explants stunted neurite outgrowth in a dose-dependent manner in accordance with previous findings in hippocampal neurons or neuroblastoma cells." (PMID 25050325, 2014). "Furthermore, treatment of neuroblastoma cells with the inflammatory cytokine interleukin-1-beta (IL-1β), a common target of NF-kB signaling and the most highly up-regulated gene in our study, failed to protect them from 6-OHDA toxicity." (PMID 23818941, 2013). "As expected, stimulation with MDP augmented IL-1β levels by neuroblastoma cells." (PMID 23940760, 2013). "Taking together, our results suggest that IL-1β production may contribute to AAP-induced caspase-dependent apoptotic neuroblastoma cell death." (PMID 23166834, 2012). "In addition, we found that AAP increased caspase-1 activity, the unique caspase that processes pro-IL-1β into mature IL-1β, in neuroblastoma cells." (PMID 23166834, 2012). "Thus, our results clearly show that AAP-induced ROS generation, NFkB activation and subsequent IL-1β production play a central role in activating the intrinsic apoptotic pathway in neuroblastoma cells." (PMID 23166834, 2012). "Therefore, in the present study, we investigated the effect of resveratrol on the production of prostanoids induced by IL-1β in SK-N-SH cells, a human neuroblastoma cell line." (PMID 19751497, 2009). "Interestingly, treatment with BUVEC-CM, even in the lowest concentration (25%), could diminish IL-1β production in the human neuroblastoma-derived SH-SY5Y cell lines (p < 0.0001)." (PMID 35202301, 2022). "It has been reported that TNF-α itself has the capability to induce reactive oxygen species-dependent inflammasome activation and IL-1β production in neuroblastoma cells, which could support the idea that NLRP3 is secreted out of the cell upon TNF-α-mediated inflammasome activation." (PMID 32271889, 2020). "However, considering that mutant SOD1 promotes apoptosis in oxidatively stressed neuroblastoma N2a cells by activating caspase-1 and increasing mature IL-1β secretion, we postulate that AAP-induced ROS production may be responsible for caspase-1 activation." (PMID 23166834, 2012).